CD38 (CD38 molecule)
Diseases named in the same sentence as CD38 in open-access papers (continued):
Sharing a sentence is not in itself a finding about the gene and the disease.
diabetic cardiomyopathy (1 paper, 2023). Diabetic cardiomyopathy is a disorder of the heart muscle in people with diabetes. "In order to elucidate the mechanisms of CD38 deficiency protecting against diabetic cardiomyopathy, we first examined the expression of the genes involved in pyroptosis in heart tissues from CD38-deficient mice under normal and diabetic conditions." (PMID 37958991, 2023). "CD38-KO mice were used to investigate a direct relationship between CD38 deficiency and diabetic cardiomyopathy." (PMID 37958991, 2023). "CD38 deficiency alleviated HFD plus streptozotocin (STZ)-induced diabetic cardiomyopathy." (PMID 37958991, 2023). "Next, we further determined whether the deficiency of CD38 protects the heart against diabetic cardiomyopathy." (PMID 37958991, 2023). "Furthermore, we demonstrated that the protective roles of CD38 deficiency on diabetic cardiomyopathy were related to the inhibition of apoptosis and pyroptosis through activating Sirt3/FOXO3a signaling pathways." (PMID 37958991, 2023). "Taken together, these results indicated that CD38 deficiency mediated the decrease in pyroptosis and apoptosis in diabetic cardiomyopathy, which might be associated with activating sirtuin-signaling pathways." (PMID 37958991, 2023). "To further clarify the protective roles of CD38 in diabetic cardiomyopathy in vitro, we examined the effects of CD38 on high glucose plus palmitic acid (HG/PA)-induced cardiomyocytic damage using CD38 knockdown H9C2 stable cell lines." (PMID 37958991, 2023). "Here, we report that global deletion of the CD38 gene significantly prevented diabetic cardiomyopathy induced by high-fat diet plus streptozotocin (STZ) injection in CD38 knockout (CD38-KO) mice." (PMID 37958991, 2023). "And the new understanding of the role of CD38 in diabetic cardiomyopathy may have potential guiding significance for clinical treatment of the disease." (PMID 37958991, 2023).
endometrial tumors (1 paper, 2022). "CD8+ T cells, CD20+ B cells, CD4+ T cells, and CD38+ PCs were common in endometrial tumors." (PMID 34689225, 2022).
endometriosis (1 paper, 2023). The growth of functional endometrial tissue in anatomic sites outside the uterine body. "In the same study, peritoneal fluid CD8+ MAIT cells from endometriosis patients displayed higher levels of the activation marker CD38, when compared to non-endometriosis participants (2.98 ± 0.53 vs 0.36 ± 0.09, respectively; p = 0.0071)." (PMID 37497226, 2023).
energy metabolism disorder (1 paper, 2022). "Energy metabolism disorder caused by CD38 overactivation occurs in senescent Iba1 + microglia, which reduces their ability to phagocytose and clear senile plaque deposits." (PMID 35241173, 2022). "The expression of CD38 increases in senescent BV2 cells, resulting in energy metabolism disorder." (PMID 35241173, 2022).
Epstein-Barr virus infection (1 paper, 2017). An infection that is caused by Epstein-Barr virus. "Additionally, the pathway ‘Epstein-Barr virus infection’ was simultaneously enriched, in which several genes including BCL2, CD39, HSP70, HDAC45, IL10, IL10R and vimentin were up-regulated, together with some down-regulated genes such as CD38, NUP214, RBP-Jκ, CycA, TAK1 and TBK1." (PMID 28912500, 2017).
Erythema (1 paper, 2025). Redness of the skin, caused by hyperemia of the capillaries in the lower layers of the skin. "Four hours following the application of CD38‐EVs‐DoxMNs to the skin of depilated mice under constant pressure, the skin pores closed naturally, showing no signs of fever, erythema, red spots, scales or blisters." (PMID 40317915, 2025).
esophageal tumors (1 paper, 2020). "Noteworthy also CD38 is overexpressed in primary esophageal tumors and represents a known mechanism of resistance to PD-1/PD-L1 blockade." (PMID 31960110, 2020).
falciparum malaria (1 paper, 2020). "In naturally infected adults with acute malaria, a prominent population of type 1 regulatory T cells arises that can be defined by high co‐expression of CD4 and CD38 (CD4hiCD38hi) and that correlates with disease severity in patients with falciparum malaria." (PMID 33282291, 2020).
focal segmental glomerulosclerosis (1 paper, 2026). A renal disorder characterized by sclerotic lesions in the glomeruli. "Daratumumab, an anti-CD38 monoclonal antibody targeting plasma cells, has emerged as a potential therapy for recurrent focal segmental glomerulosclerosis (FSGS) after kidney transplantation; however, data on subcutaneous administration and its use in de novo disease are limited." (PMID 42239817, 2026).
food allergy (1 paper, 2024). Gastrointestinal disturbances, skin eruptions, or shock due to allergic reactions to allergens in food. "We tested CD38 expression on Tregs, TFR cells, and TFH cells in our food allergy model and found that Tregs have a high level of CD38 expression, and this level is increased on TFR cells." (PMID 39377224, 2024).
glomerulonephritis (1 paper, 2018). A renal disorder characterized by damage in the glomeruli. "Furthermore, the production of anti-single-stranded DNA and anti-nuclear RNP (nRNP) autoantibodies, the development of glomerulonephritis, and the expression of IFN-I-stimulated genes (ISGs) were also greatly attenuated in pristane-treated Cd38−/− mice." (PMID 29463868, 2018).
gram-positive bacterial infections (1 paper, 2019). Infections caused by bacteria that retain the crystal violet stain (positive) when treated by the gram-staining method. "Several evidences have already proved the role CD38 played in responding to Gram-positive bacterial infection." (PMID 30915370, 2019).
H1N1 virus infection (1 paper, 2011). "In order to measure the degree of T-cell activation during 2009 pandemic H1N1 virus infection, we assessed the percentage of CD4+ and CD8+ cells that expressed the activation markers CD38/HLA-DR." (PMID 21625541, 2011).
helminth infection (1 paper, 2014). "We observed substantial differences in the expression of immune activation markers (HLA-DR and CD38) on T cells between different helminth infections." (PMID 24675895, 2014). "Blinded to helminth infection status, T cell differentiation (CD45RO, CD27), activation (HLA-DR, CD38) and CCR5 expression was determined at baseline and 3 months after Albendazole/Praziquantel treatment." (PMID 24675895, 2014). "Nonetheless, in subjects with helminth infection the median proportion of HLA-DR+/CD38+ CD4 T cells was significantly elevated (2.16% versus 2.63%, p = 0.011) whereas median HLA-DR+/CD38+ CD8 T cell frequencies were moderately increased (5.50% versus 6.86%, p = 0.055)." (PMID 24675895, 2014). "Independent of helminth infection status, CD38 expression alone was a characteristic of “naïve” CD27−/CD45RO− CD4 and CD8 T cells, whereas co-expression with HLA-DR was exclusively detected on memory T cells." (PMID 24675895, 2014). "We compared the frequencies of HLA-DR+ and HLA-DR+/CD38+ on CD4 and CD8 T cells and in addition studied the CCR5 expression density on CD4 T cells at 1–3 months in subjects with and without helminth infection at baseline." (PMID 24675895, 2014).
Hepatomegaly (1 paper, 2025). Abnormally increased size of the liver. "Our results revealed that significantly higher PDL1 expression on CD34+/CD38- LSCs but not on blasts was associated with hepatomegaly (P = 0.028)." (PMID 40940644, 2025).
HIV encephalopathy (1 paper, 2016). "CD38 up-regulation was demonstrated by immune-histo-chemical analysis in brain tissue from HIV encephalopathy (HIVE) patients." (PMID 27405321, 2016).
hypertriglyceridemia (1 paper, 2020). A laboratory test result indicating elevated triglyceride concentration in the blood. "Patient 3 stopped the study drug due to hypertriglyceridemia and lack of response; however, she had evidence of significantly increased CD38 expression on the leukemic blasts from the bone marrow aspirate obtained at the end of cycle 1, suggestive of leukemic blast maturation." (PMID 33194741, 2020).
hyperuricemia (1 paper, 2024). An abnormally high level of uric acid. "In addition, we cannot exclude the possibility that long-term and crystal-free hyperuricemia (>420 μM) in humans may overly modulate additional unknown targets, especially in CD38-negative cells, thereby partially covering the CD38-mediated physiological functions of sUA." (PMID 39527634, 2024).
idiopathic inflammatory myopathies (1 paper, 2025). "Daratumumab, an anti-CD38 monoclonal antibody primarily used in hematologic malignancies, has recently shown promise in very few case reports of refractory idiopathic inflammatory myopathies." (PMID 40308381, 2025).
immune thrombocytopenic purpura (1 paper, 2022). "In immune thrombocytopenic purpura (ITP), the expression of CD38 and CD56 is significantly lower before treatment than after it." (PMID 36077708, 2022).
keloid (1 paper, 2021). An irregularly shaped, elevated mark on the skin caused by deposits of excessive amounts of collagen during wound healing. "The increased levels of markers such as CD9, CD38 and CD39 in keloid and perilesional tissue potentially indicated that also these cells had started to differentiate." (PMID 34502327, 2021).
large-cell lymphoma (1 paper, 2022). "One patient (case 4) demonstrated a large-cell lymphoma with immunoblastic morphology and the expression of CD19, CD20, MUM1, CD38 and partial CD138, most consistent with LBCL with plasmablastic features." (PMID 36013165, 2022).
Lassa fever (1 paper, 2020). A viral hemorrhagic fever that is caused by the Lassa virus, which is transmitted by contact with infected rodents; it is characterized by fever, headache, malaise, myalgia, and hearing loss. "We observed a discrete subset of EBV-specific CD8 T cells that expressed CD38 during LASV infection but not in healthy controls, suggesting that non-LASV-specific T-cell activation indeed occurred during acute Lassa fever." (PMID 32817220, 2020).
learning disability (1 paper, 2016). A group of disorders that affect a person's ability to learn or process specific types of information which is in contrast to his/her apparent level of intellect. "Moreover, a recent study showed that a genetic deletion involving CD38 is associated with mild learning disability, suggesting that CD38 deficiency may result in intellectual deficits in addition to the ASD-related phenotypes." (PMID 26856703, 2016).
leishmaniasis (1 paper, 2010). Infectious disease that is transmitted through the bite of hematophagous female phlebotomine sand flies. "The finding of high CD38 levels positively correlated with Leishmania infection reinforces the idea that leishmaniasis can be a cofactor to of this heightened activation status." (PMID 21171992, 2010). "Multivariate linear regression analysis to evaluate the association between T cell activation (CD38+ on CD8+ T lymphocytes) and independent variables in leishmaniasis and HIV-1 co-infected patients." (PMID 21171992, 2010). "HIV-1 co-infected individuals (AVL and ATL), had a significantly higher percentage of CD8+ T cells that expressed CD38 when compared to HIV-1 infected patients without leishmaniasis (median 55.8%; [49% - 64%], p < 0.05)." (PMID 21171992, 2010). "Furthermore, the prognostic value of CD38 expression on CD8+ T cells might not be useful in predicting HIV-1 progression in co-infected patients since these molecules levels stay elevated after clinical remission of leishmaniasis." (PMID 21171992, 2010). "Therefore, we investigated whether leishmaniasis could impact T lymphocytes activation in HIV-1 co-infected patients through the analysis of CD4+ T absolute counts and of the proportion of CD8+ T cells expressing CD38 in Leishmania/HIV co-infected patients recovered after anti-leishmanial therapy." (PMID 21171992, 2010).
liver steatosis (1 paper, 2021). "In order to elucidate the mechanisms of the anti-hepatic steatosis of CD38 deficiency, we first examined the expressions of the genes involved in fatty acid oxidation in liver tissues from CD38-/- mice fed with HFD." (PMID 34803499, 2021). "Here, we first examined the effects of CD38 deficiency on HFD-induced hepatic steatosis in CD38-/- mice." (PMID 34803499, 2021). "Obviously, our findings provided an insight in elucidating the underlying mechanisms of NAFLD development and the CD38 may be a possible target for preventing liver steatosis and NAFLD." (PMID 34803499, 2021). "As we expected, deletion of CD38 significantly alleviated HFD-induced hepatic steatosis via reducing lipid accumulation and oxidative stress in liver." (PMID 34803499, 2021). "Here, we reported that CD38-/- mice significantly alleviated HFD-induced hepatic steatosis." (PMID 34803499, 2021). "In contrast, overexpression of CD38 aggravated OA-induced hepatic steatosis and oxidative stress." (PMID 34803499, 2021). "HFD or oleic acid (OA) remarkably increased the mRNA and protein expressions of CD38 in mouse hepatic tissues and primary hepatocytes or hepatic cell lines in vitro and in vivo, suggesting that CD38 might play a role in HFD-induced hepatic steatosis." (PMID 34803499, 2021).
Lymphatic Metastasis (1 paper, 2021). Transfer of a neoplasm from its primary site to lymph nodes or to distant parts of the body by way of the lymphatic system. "The percentages of CD38+ CD45+ leukocytes (p = 0.0604) tended to be higher in the PB of patients without lymphatic metastasis." (PMID 35116020, 2021).
lymphoblastic lymphoma (1 paper, 2025). A lymphoma composed of immature small to medium-sized precursor lymphoid cells (lymphoblasts). "Daratumumab, a monoclonal antibody targeting CD38, has shown promising preclinical and early clinical activity in pediatric hematologic malignancies, including T-ALL and lymphoblastic lymphoma." (PMID 41373522, 2025).
mastocytosis (1 paper, 2021). A clonal myeloproliferative neoplasm characterized by the proliferation and accumulation of neoplastic mast cells in one or multiple organs or organ systems. "In mastocytosis, MCs differed in their levels of CD38 content." (PMID 34685490, 2021). "In mastocytosis, CD38 is more often expressed in hypochromic MCs containing small granules." (PMID 34685490, 2021).
mediastinal tumor (1 paper, 2025). "Histopathological confirmation was obtained from the gastric mass (CD138+/CD38+ plasma cell infiltration) and anterior mediastinal tumor (κ light chain restriction)." (PMID 40901511, 2025).
medulloblastoma (1 paper, 2019). A malignant, invasive embryonal neoplasm arising from the cerebellum. "CD1d, CD38, and CD81 showed interesting expression profiles in the primary screen but have not been identified as markers of medulloblastoma and so they, along with CD117’s low expression in Ptch1 deleted cells, were not further investigated in this study." (PMID 30657775, 2019).
metastatic melanoma (1 paper, 2024). A melanoma that has spread from its primary site to another anatomic site. "Phenotypic, functional, and single-cell transcriptomic analysis of intratumoral CD8+ T cells from both immunotherapy-resistant pre-clinical models and metastatic melanoma patients identifies that CD38-expressing CD8+ T cells are associated with anti-PD1 resistance." (PMID 38451948, 2024). "Moreover, CD8+ T cells co-expressing PD1 and CD38 (PD1+CD38hiCD8+ T cells) have been identified as a dysfunctional T cell subset that inversely correlates with the therapeutic responsiveness of anti-PD1 therapy in patients with metastatic melanoma." (PMID 38451948, 2024). "Recently, a CD4+ T cell subset co-expressing CD38 and CD39 was also observed in metastatic melanoma patients resistant to anti-PD1 therapy." (PMID 38451948, 2024).
Miscarriage (1 paper, 2025). A pregnancy that ends at a stage in which the fetus is incapable of surviving on its own, defined as the spontaneous loss of a fetus before the 22th week of pregnancy. "Prior miscarriage history was also associated with increased levels of activated PD-1+ CD38+ HLA-DR+ cTfh cells and activated PD-1- CD38- HLA-DR+ cTfc cells." (PMID 41041305, 2025).
myelofibrosis (1 paper, 2021). A partial or complete replacement of the bone marrow stroma by fibrous tissue. "A murine model incorporating a humanised ossicle niche has demonstrated engraftment of myelofibrosis from the CD34+, CD38− HSC population only, with no engraftment in the CD34+, CD38+ progenitor population, suggesting that the initiating cell resides within this HSC population." (PMID 34193229, 2021).
myeloid sarcoma (1 paper, 2025). A tumor mass composed of myeloblasts or immature myeloid cells. "Histopathology showed blast cell infiltration with strong CD7, CD38, CD43, CD45, and BCL-2 positivity, consistent with myeloid sarcoma." (PMID 41234969, 2025). "Histopathological evaluation revealed diffuse infiltration of blast cells in the submucosa with strong positivity for CD7, CD38, CD43, CD45, and BCL-2, mild positivity for CD33, and partial positivity for CD79a, CD68, CD117, and PAX5, consistent with myeloid sarcoma." (PMID 41234969, 2025).
nonalcoholic steatohepatitis (1 paper, 2021). "Here, the discussion is focused on roles of AHR and CD38 in NAFLD and NASH (nonalcoholic steatohepatitis)." (PMID 34559251, 2021).
osteomyelitis (1 paper, 2024). An acute or chronic inflammation of the bone and its structures due to infection with pyogenic bacteria. "As IgD + CD38− B cells represent a subpopulation of mature naive B cells primed for activation, their decline may attenuate acute inflammatory responses to osteomyelitis-causing pathogens." (PMID 38650858, 2024).
pancreatitis (1 paper, 2024). Inflammation of the pancreas. "has suggested that aberrant intracellular Ca2+ release mediated by CD38 contributes to bile acid-induced pancreatitis and acinar cell injury." (PMID 39620226, 2024).
periapical granuloma (1 paper, 2018). Chronic nonsuppurative inflammation of periapical tissue resulting from irritation following pulp disease or endodontic treatment. "CD38+ cells representing lymphocytes and plasma cells dominated the infiltrated immune cell population in the refractory periapical granuloma which is consistent with most studies." (PMID 30631444, 2018). "CD38+ cells expressing TLR2+ (CD38+/TLR2+) were identified in all eight periapical granuloma samples and were abundant throughout the lesion." (PMID 30631444, 2018). "All the periapical granuloma samples showed CD38+ cells and had the same staining pattern as the CD38+ cells in the lingual tonsil." (PMID 30631444, 2018). "The protocol for immunohistochemical procedures of TLR2, CD38, CD68 and CD83 have been standardized and the expression of each cell marker (TLR2, CD38, CD68 and CD83) within refractory periapical granuloma was identified." (PMID 30631444, 2018). "Refractory periapical granuloma consistently expressed TLR2 through lymphocytes and plasma cells (CD38+), macrophages and monocytes (CD68+) and mature dendritic cells (CD83+)." (PMID 30631444, 2018).
plasma cell leukemia (1 paper, 2011). An aggressive plasma cell neoplasm characterized by the presence of neoplastic plasma cells in the peripheral blood. "In addition, HuMax-CD38 inhibits the CD38 ADP-ribosyl cyclase activity in target cells, which may contribute to the effectiveness of HuMax-CD38 in killing both primary MM and plasma cell leukemia cells." (PMID 22046572, 2011).
preeclampsia (1 paper, 2020). Preeclampsia is a hypertensive disorder of pregnancy that is characterized by new-onset hypertension with proteinuria presenting after 20 weeks of gestation, and depending on mild or severe forms may initially present with severe headache, visual disturbances, and hyperreflexia. "The expression of CD45 and CD38 was significantly higher in the control group compared to the preeclampsia group (p = 0.000; p = 0.000)." (PMID 32650736, 2020).